CCNB3P1 (cyclin B3 pseudogene 1)
Gene: Processed pseudogene on chromosome 5 (26,739,753 to 26,741,183, reverse strand). Ensembl gene ENSG00000249616.
Diseases named in the same sentence as CCNB3P1 in open-access papers:
CCNB3P1 is named in the same sentence as 1 disease in open-access papers, as found by Europe PMC text mining. Sharing a sentence is not in itself a finding about the gene and the disease. The quoted sentences say what the papers report.
mood disorder (1 paper, 2025). A cognitive disorder a disturbance in which the person's mood is hypothesized to be the main underlying feature. "The pseudogene CCNB3P1 may affect self-harm via neuronal health, and ANPEP influences neuropeptide metabolism linked with mood disorders." (PMID 40125487, 2025).